CYP2G1P (cytochrome P450 family 2 subfamily G member 1, pseudogene)
Synonyms: CYP2GP1; formerly CYP2G1
Gene: Transcribed unprocessed pseudogene on chromosome 19 (40,891,219 to 40,900,155, forward strand). Ensembl gene ENSG00000130612.
Diseases named in the same sentence as CYP2G1P in open-access papers:
CYP2G1P is named in the same sentence as 1 disease in open-access papers, as found by Europe PMC text mining. Sharing a sentence is not in itself a finding about the gene and the disease.
CYP2G1P shares sentences with these, for which no sentence is quoted: depression (1 paper).